PIK3CA (phosphatidylinositol-4,5-bisphosphate 3-kinase catalytic subunit alpha)
Diseases named in the same sentence as PIK3CA in open-access papers (continued):
Sharing a sentence is not in itself a finding about the gene and the disease.
bladder cancer (continued). "In addition to the PIK3CA mutations, we found signatures 2 and 13 to be associated with ERBB2 p.S310F (c.929C>T) mutation in bladder cancer, and signature 13 to be associated with PPP2R1A p.P179R (c.536C>G) mutation in uterine corpus endometrial carcinoma." (PMID 30412573, 2018). "In conclusion, our findings suggest that PIK3CA rs6443624, AKT1 rs2498801, AKT1 rs1130233, as well mTOR rs2295080 polymorphism may be related to bladder cancer development in a sample of Iranian population." (PMID 29383014, 2018). "Therefore, this case-control study was designed to assess the possible association between PIK3CA, AKT1 and mTOR polymorphisms and susceptibility to bladder cancer in an Iranian population." (PMID 29383014, 2018). "Our findings strongly suggest that targeting of PIK3CA maybe a valid therapeutic approach in advanced bladder cancer." (PMID 27465249, 2016). "Mutant PIK3CA is a potent oncogenic driver in many UC cell lines and may represent a valuable therapeutic target in advanced bladder cancer." (PMID 27465249, 2016). "Our objective was to examine the effects of specific inhibition of mutant PIK3CA in bladder tumor cells to determine whether mutant PIK3CA can be considered a valid therapeutic target in bladder cancer." (PMID 27465249, 2016). "Notably, the authors indicated that a limitation of the study was the low frequency of mutations in the PIK3CA gene (approximately 13%), which does not reflect the general occurrence of these variants in bladder cancer cases." (PMID 39768623, 2024). "In addition, PIK3CA also enhances the growth and metastasis of bladder cancer in vivo." (PMID 37627900, 2023). "this study shows clearly that mutations in AKT1 and PIK3CA are rare events and could not be considered as valuable biomarkers for bladder cancer management." (PMID 35317488, 2022). "Thus, as an oncogene, PIK3CA may serve as a potential target for the diagnosis and treatment of bladder cancer." (PMID 33344221, 2020). "No matter the mechanism though, the fact that TTI1 (28%) is overexpressed and kinase-PIK3Ca signaling (72%) is altered in a significant number of bladder cancer cases indicates that reducing the chaperone activity that supports this axis may be viable approach to treating MIBC." (PMID 30220976, 2018). "In bladder cancer, previous reports have also observed that C > T base substitutions were most common in FGFR3 and PIK3CA." (PMID 39410541, 2024). "Among the top ten genes, PIK3CA, RYR2, and KMT2C were highly expressed in the bladder cancer compared to normal bladder tissue (P < 0.001)." (PMID 33344221, 2020). "The panel of cell lines included in our study possesses diverse molecular alterations in FGFR3, RAS, PIK3CA, PTEN, TSC1 and mTOR that are capable of influencing response to PI3K pathway inhibition and are very frequent in bladder cancer specimen." (PMID 29357370, 2018).
bladder cancer (continued). "A total of nine chr3p25 and chr11p11 genes were functionally connected to genes in the KEGG bladder cancer pathway (E2F1, E2F3, EGFR, RAF1, RB1) or to other cancer-related genes (AKT2, PIK3CA, RB1, TRIO)." (PMID 29140994, 2017). "Here we show, using clinical samples and bladder cancer cell lines, a functional interaction between EZH2- and PIK3CA-dependent signaling pathways." (PMID 28060766, 2017). "Although there are no PIK3CA-targeted drugs specifically approved for bladder cancer, different PI3K inhibitors have been approved by FDA, but not in monotherapy for solid tumours, including bladder cancer." (PMID 41008920, 2025). "This co-occurrence suggests a complex interaction between these genes, but it does not establish PIK3CA as a standalone predictive marker for recurrence-free survival in bladder cancer patients." (PMID 39768623, 2024). "Elevated phosphorylation of AKT1/2 is observed in 40–50% of bladder cancer cases, independent of PIK3CA or PTEN alterations, and may result from upstream receptor tyrosine kinase (e.g., FGFR3 or EGFR) activation." (PMID 41438986, 2025). "It revealed same outcome like above that, PIK3CA knockdown weaken the proliferation, migration, invasion and angiogenesis capabilities of EJ and T24T cells, however restoration of CUX1 overexpression rescued bladder cancer cells from their defects resulted from knockdown of CUX1." (PMID 33344221, 2020). "Interestingly, there are no literature reports of PIK3CA regulation by CUX1 in bladder cancer." (PMID 33344221, 2020).
squamous cell carcinoma (86 papers, 2009 to 2026). A carcinoma arising from squamous epithelial cells. "Less common mutations, such as NRAS and PIK3CA, also warrant additional investigation in adenocarcinoma and squamous cell carcinoma, potentially through targeted clinical trials." (PMID 40502411, 2025). "PIK3CA mutations are prevalent in various gynecological cancers, including cervical adenocarcinoma and squamous cell carcinoma." (PMID 40647429, 2025). "Compared with those in adenocarcinoma, PIK3CA mutations are more common in squamous cell carcinoma (SCC), which arises from stratified squamous epithelia that are usually exposed to adverse environmental factors." (PMID 38616230, 2024). "Activating mutations in PIK3CA have been detected in 4%–7% of NSCLCs, amplification in more than 30% of squamous cell carcinomas, and about 1% of adenocarcinomas." (PMID 38515456, 2024). "At the age of 56, due to intervening clonal mutations in PIK3CA background, she developed a squamous cell carcinoma in the right affected leg which was treated surgically." (PMID 37662840, 2023). "A number of studies showed that mutations within PIK3CA gene were found in multiple HPV-induced squamous cell cancers, such as head and neck cancers, cervical, and anal cancers." (PMID 37177979, 2023). "According to a large cohort study, certain NSCLC subtypes, such squamous cell carcinoma, exhibit a higher prevalence of PIK3CA mutations than others." (PMID 37096065, 2023). "The 3q amplicon contains key oncogenic driver genes such as TP63, SOX2, PIK3CA, which are implicated in all squamous cell carcinomas, including ESCC." (PMID 37444412, 2023). "In the present study, coexisting KRAS and PIK3CA mutations were found in 17.1% of patients; in more than half with squamous cell carcinoma." (PMID 37108122, 2023). "Squamous cell carcinomas (n = 389) exhibited a significantly higher PIK3CA mutation rate of 45.2% compared with 19.8% in non-squamous cell carcinomas (n = 420)." (PMID 38201563, 2023). "Large studies of NSCLC patients by next-generation sequencing (NGS) identified PIK3CA gene mutations in 3.7% of patients, with predominance for squamous cell carcinoma (8.9%) compared with adenocarcinoma (2.9%)." (PMID 38033496, 2023). "The EGFR (Val592Ile), PIK3CA (Arg19Ile), PIK3CA (Arg852Pro), and ROS (Trp847Leu) mutations were assessed only in patients with squamous carcinoma." (PMID 36422072, 2022). "EGFR (Val592Ile), PIK3CA (Arg19Ile), PIK3CA (Arg852Pro), and ROS (Trp847Leu) mutations were present only in the squamous carcinoma population." (PMID 36422072, 2022). "Activating mutations in PIK3CA result in the activation of the phosphoinositide 3-kinases/protein kinase B/mTOR pathway, which is commonly seen in other organs’ squamous cell carcinomas." (PMID 33482222, 2021). "Further to this, for the cases exhibiting a PIK3CA mutation, five were squamous cell carcinoma and the remaining five were adenocarcinoma." (PMID 32756609, 2020). "Among squamous cell carcinoma cases, mutations of the genes only accounted for 5% with PIK3CA exhibited the highest rate of mutation (2.53%)." (PMID 32756609, 2020).
squamous cell carcinoma (continued). "Initial reports of PIK3CA gene mutations in esophageal cancers demonstrated that these mutations were present in 12% of squamous cell carcinomas and 6% of adenocarcinomas of the esophagus." (PMID 31905960, 2019). "In our study population, AKT1 and PIK3CA mutations were only found in squamous cell carcinomas, with frequencies of 2.6% and 10.5%, respectively." (PMID 31668020, 2019). "An initial study reported PIK3CA mutational frequency of 11% in squamous cell carcinoma in pharyngeal cancer samples." (PMID 31905960, 2019). "Somatic mutations in PIK3CA have been reported in low frequencies in Vulvar squamous cell carcinoma." (PMID 31905960, 2019). "In our study, 13.5% of cases were identified as having a PIK3CA mutation or amplification, all of which presented squamous cell carcinoma histology." (PMID 30115035, 2018). "PIK3CA was mutated in 5.26% of adenocarcinoma patients and 15.87% of squamous cell carcinoma patients from the Irish cohort and 4.6% of total ETOP cases." (PMID 27765909, 2016). "In our patient cohort, we found significantly more frequent somatic KRAS mutations in cervical adenocarcinoma, whereas PIK3CA mutations were more frequently found in squamous cell carcinoma (manuscript submitted)." (PMID 25795131, 2015). "Recently, some studies reported an incidence of PIK3CA mutations in other squamous cell cancers similar to that observed in our study." (PMID 24642661, 2014). "Heterozygous mutations in PIK3CA gene were found in three cases (5%) of squamous cell carcinoma at codons 527 (GAC > AAC, Asp > Asn) and 545 (GAG > AAG, Glu > Lys; GAG > GCG, Glu > Ala)." (PMID 25220666, 2014). "Patients with adenocarcinoma had fewer PIK3CA mutations (14%), and survived longer (median, 14.2 months) than those with squamous cell carcinoma (48% and 7.2 months; p = 0.016, and 0.001, respectively)." (PMID 25426553, 2014). "Most notably squamous cell carcinomas are mostly commonly associated with smoking history and are marked by amplification of PIK3CA and p63; whereas adenocarcinomas are associated with a high frequency of mutations in KRas and EGFR." (PMID 24123619, 2013). "PIK3CA was the most frequently mutated gene in our cervical adenocarcinoma cohort (n = 26, 25.5%), a finding consistent with previous studies showing PIK3CA mutation rates of 25–42% in cervical adenocarcinoma and squamous cell carcinoma." (PMID 41597409, 2026). "Additionally, specific subtypes are characterized by different mutations: adenocarcinoma typically exhibits changes in the EGFR and ALK genes, while squamous cell carcinoma is associated with alterations in the PIK3CA and FGFR1 genes." (PMID 38339175, 2024). "Finally, cervical HPV-associated cases, particularly those exhibiting a squamous cell carcinoma subtype were more altered for the PIK3CA gene (60%)." (PMID 36010253, 2022). "It was reported that PIK3CA mutations could confer a relapse-free survival advantage for squamous cell carcinoma in NSCLC." (PMID 33973529, 2021). "Additionally, data generated from cBioPortal revealed that the PIK3CA mutation showed a high alteration rate in squamous cell carcinoma, adenocarcinoma, adenosquamous carcinoma and mucinous adenocarcinoma compared to endometrioid carcinoma." (PMID 31295843, 2019). "PIK3CA mutation was found in 3.9% of squamous cell carcinoma and 2.7% of adenocarcinoma." (PMID 24533074, 2014).
squamous cell carcinoma (continued). "Indeed, activating mutations in NFE2L2 have recently been discovered to commonly co-occur with PIK3CA amplification and mutation in multiple squamous-cell carcinomas including lung, and cooccurrence contributed to greater sensitivity to knockout of either gene in cell lines." (PMID 35872531, 2022). "Further analyses revealed that patients with squamous cell carcinomas were significantly younger and more likely to carry PIK3CA mutations than those with adenocarcinomas (p = 0.034 per independent samples t-test for age and p = 0.016 per Fisher's exact test for PIK3CA mutations, respectively)." (PMID 25426553, 2014). "In addition, multiplex testing for driver mutations in 72 squamous cell carcinomas of the lung detected: PIK3CA mutations in 8%, PTEN mutation/deletion in 28%, FGFR1 amplification in 26%, and unknown genetic alterations in 39%." (PMID 25348872, 2014). "In contrast, PIK3CA mutations and copy number gains of components of FGFR signaling pathway have been described as oncogenic drivers of squamous cell carcinoma of different origin including lung, head and neck, and stomach." (PMID 37249797, 2023). "On the other hand, squamous cell carcinoma cases of the cervix were entirely HPV-associated and mutations occurred in the PIK3CA (60%) gene, whereas mucinous carcinomas were HPV-independent and mostly exhibited alterations in the STK11 gene." (PMID 36010253, 2022). "The locus 3q26.32 harboring PIK3CA and neighboring loci at the long arm of chromosome 3 are the most commonly amplified chromosome regions in squamous carcinomas of the uterine cervix." (PMID 34436017, 2021). "Alternatively, squamous-cell carcinoma is commonly caused by EGFR amplification, phosphatidylinositol-4,5-bisphosphate 3-kinase catalytic subunit alpha (PIK3CA) amplification and MET amplification." (PMID 32316322, 2020). "Comparing expression levels across TCGA datasets revealed that PIK3CA is relatively highly expressed in squamous cell carcinomas compared to adenocarcinomas across various cancer types." (PMID 32974170, 2020). "The EDF genes specific for the histology subtype also include TSHR, KEAP1, and EGFR in adenocarcinoma, and NOTCH1, PIK3CA in squamous cell carcinoma." (PMID 33078899, 2020). "PIK3CA amplifications were most prevalent in keratinizing squamous cell carcinoma (KSC) patients (64.3%, 27/42, P = 0.015), followed by basaloid squamous cell carcinoma (BSC) (50%, 4/8) and nonkeratinizing squamous cell carcinoma (NKSC) (33.3%, 9/27)." (PMID 31692283, 2020). "In this study, PIK3CA amplifications were also more common in patients with squamous cell carcinoma (33.1%) compared with adenocarcinoma (6.2%)." (PMID 31989769, 2020). "The purpose of this study was to evaluate PD-L1, FGFR1, PIK3CA, PTEN, and p16 expression in squamous cell carcinoma (SCC) associated with emphysema/COPD." (PMID 31481045, 2019).